PTH (parathyroid hormone)
Diseases named in the same sentence as PTH in open-access papers (continued):
Sharing a sentence is not in itself a finding about the gene and the disease.
breast carcinoma (continued). "The expression of PTH/PTHrP receptor by breast cancer cells suggests that PTHrP may be a paracrine/autocrine regulator of breast carcinoma." (PMID 7599071, 1995). "The four-way decomposition mediation analysis showed a suggestive mediation through estradiol and PTH in the association of NO2 and PCB153 exposures with breast cancer risk, whereas albumin, estradiol, LDL and HDL cholesterol may play a role in the association between BaP and breast cancer risk." (PMID 39548533, 2024). "A few studies have suggested that PTH might be involved in the development of breast cancer." (PMID 39548533, 2024). "It had been reported that parathyroid hormone (PTH) and parathyroid hormone receptors stimulated the proliferation of some tumor cells, such as osteoblasts, human renal carcinoma cell and breast cancer cells, indicating excessive parathyroid hormone might be pro-carcinogenic to some extent." (PMID 35663394, 2022). "There was no clear association between PTH and breast cancer mortality." (PMID 24952509, 2014). "In the presence of conditioned medium from breast cancer cells, HU308 and JWH133 enhanced parathyroid hormone-induced osteoblast differentiation and the ability to support osteoclast formation." (PMID 40275168, 2025). "Mechanistically, intermittent PTH treatment altered the metastatic gene expression profile in MC3T3-E1 osteoblastic cells and attenuated the migratory potential of breast cancer cells towards osteoblasts." (PMID 36692956, 2023). "All breast cancer cell lines had at least 10-fold lower PTHR1 mRNA levels than MC3T3-E1 cells, which have a robust cAMP response to exogenous PTH and PTHrP treatment." (PMID 29867773, 2018). "Intermittent PTH also did not reduce bone metastasis when expression of PTH1R was knocked down in 4T1 murine breast cancer cells by shRNA." (PMID 36692956, 2023). "With regard to PTH, we found no statistic differences between breast cancer patients at the initial diagnosis and healthy women." (PMID 25923354, 2015). "Serum levels of 25(OH) D and PTH (available, respectively, for 44% and 17% of women who developed breast cancer, and for 36% and 14% in the group of women who did not develop breast cancer) were not statistically different between the two groups." (PMID 23940680, 2013). "Furthermore, we noted an elevated but statistically non-significant mediated proportion for PTH in the association between both NO2 and PCB153 exposures and breast cancer risk." (PMID 39548533, 2024). "KEGG enrichment analysis of all the DEGs in networks showed that PTH and related genes were significantly enriched in the pathway of parathyroid hormone secretion, synthesis, and action while FGF2 and related genes were significantly enriched in the pathways of cancer and specifically breast cancer." (PMID 34667146, 2021). "It is not known if breast cancer cells also compete for space in the HSC niche, or whether PTH causes mobilization of tumour cells that reside in HSC niches." (PMID 30261597, 2018). "Using multiple assays, we report here that MCF7 cells, and many other breast cancer cell lines, express PTHR1 mRNA but do not bind PTH, nor do they activate cAMP formation or subsequent cAMP signaling events in response to PTH or PTHrP." (PMID 29867773, 2018). "Interestingly, evidence exists suggesting that multiple breast cancer cell lines express PTH1R at varying levels, but do not activate downstream cAMP signaling in response to PTH or PTHrP, despite functional signaling in response to calcitonin and PGE2 which serve as positive controls." (PMID 33828987, 2021).
sarcopenia (40 papers, 2015 to 2026). Progressive decline in muscle mass due to aging which results in decreased functional capacity of muscles. "In a prospective human cohort study of people aged 55 to 85 years, Visser found that the risk of sarcopenia was increased in adults with higher PTH levels and lower 25-hydroxyvitamin D levels." (PMID 40806191, 2025). "This study is the first to report the association between serum PTH levels and sarcopenia among prevalent PD patients." (PMID 39478830, 2024). "In the unadjusted model, age, ASCVD, subjective global assessment score, body mass index, relative OH, serum albumin, creatinine, phosphorus, and log-transformed intact PTH levels were significantly associated with sarcopenia." (PMID 39478830, 2024). "Association of serum intact PTH levels (continuous and categorical approach) with sarcopenia and its individual components among PD patients." (PMID 39478830, 2024). "We found that the association between elevated serum PTH levels and sarcopenia was driven by low skeletal muscle mass." (PMID 39478830, 2024). "In the sensitivity analysis adopting EWGSOP2, the association between log-transformed PTH levels and sarcopenia remained consistent (OR = 3.53, 95% CI = 1.42–8.79)." (PMID 39478830, 2024). "In the unadjusted model, age, ASCVD, BMI, relative OH, SGA, serum albumin, creatinine, phosphorus, and log-transformed intact PTH levels were significantly associated with sarcopenia." (PMID 39478830, 2024). "The primary finding revealed a linear association between elevated serum PTH levels and increased sarcopenia risk, primarily driven by low ASMI." (PMID 39478830, 2024). "Although skeletal muscle has been considered to play a minor role as a physiologically relevant PTH target, recent studies have shown that high levels of PTH in combination with low levels of vitamin D increase the risk of sarcopenia in older individuals." (PMID 38791164, 2024). "This contrasts with previous studies, which have noted an association between vitamin D and PTH levels with sarcopenia in the general population." (PMID 34579163, 2021). "The mineralizing markers FetA, Vit-D, and PTH were all associated with sarcopenia in our participants." (PMID 28112206, 2017). "Therefore, this study aimed to investigate the association between serum intact PTH levels and sarcopenia among prevalent PD patients." (PMID 39478830, 2024). "Thus, we aimed to explore the association between serum intact PTH levels and sarcopenia in PD patients." (PMID 39478830, 2024). "Our study investigated the serum PTH levels and other relevant risk factors associated with sarcopenia among prevalent PD patients, employing an updated sarcopenia consensus that comprehensively incorporates skeletal muscle mass, strength, and physical performance." (PMID 39478830, 2024). "Among PD patients, elevated serum intact PTH levels are independently associated with sarcopenia." (PMID 39478830, 2024). "Although a high parathyroid hormone level may be a risk factor for sarcopenia, the serum phosphorus concentration in such a setting remains unknown." (PMID 32438707, 2020). "Secondly, given the cross-sectional nature and complexity of CKD-MBD in our study, it is difficult to clarify whether the association between PTH and sarcopenia results from the direct detrimental effect of PTH on sarcopenia or from other CKD-MBD biomarkers influencing serum PTH levels." (PMID 39478830, 2024). "Age-related elevation in PTH levels may contribute to muscle strength and mass loss in sarcopenia." (PMID 37509715, 2023). "Levels of PTH increase with age, and it has been hypothesized that the age-related change in hormone concentration may be responsible for the loss of muscle strength and muscle mass, characteristic in sarcopenia." (PMID 34746197, 2021). "Regarding laboratory data, patients with sarcopenia had lower serum albumin, creatinine, and phosphorus levels, but higher levels of intact PTH." (PMID 39478830, 2024).
sarcopenia (continued). "A thorough comprehension of the parathyroid hormone pathway’s involvement in tuberculosis can enhance our understanding of sarcopenia’s pathogenesis." (PMID 38962681, 2024). "Across three groups of intact PTH levels (<150 pg/mL, 150–300 pg/mL, and >300 pg/mL), the prevalence rates of sarcopenia were 29.7, 36.4, and 46.2%, respectively (p for trend = 0.044)." (PMID 39478830, 2024). "After full adjustment, individuals with intact PTH levels >300 pg/mL exhibited a 4.74-fold increased odds ratio (95% CI = 1.53–14.70) for sarcopenia, compared to the reference group with intact PTH levels <150 pg/mL." (PMID 39478830, 2024). "After eliminating handgrip strength, 6-m walk, and skeletal muscle index, the best three features for sarcopenia identification of male patients are age, fasting blood glucose, and parathyroid hormone." (PMID 36788486, 2023). "Previous studies indicated that elevated PTH concentration is associated with worse performance in the TUG test, lower gait speed, higher risk of sarcopenia, increased instability, and fall risk." (PMID 35514345, 2022). "A significant body of experimental and clinical evidence from the general population indicates the key role of parathormone (PTH) and vitamin D on skeletal muscle health; thus, CKD-MBD components have emerged as important sarcopenia risk factors in dialysis patients." (PMID 40142260, 2025). "Regarding the individual components of sarcopenia, serum PTH levels were significantly associated with low ASMI, but not with low HGS and slow GS." (PMID 39478830, 2024). "Moreover, conducting more comprehensive studies is crucial to dissect the role of PTH in sarcopenia." (PMID 39478830, 2024). "However, no studies have explored the relationship between serum intact PTH levels and sarcopenia in peritoneal dialysis (PD), in which the pattern of serum PTH changes differs from that of HD." (PMID 39478830, 2024). "A linear relationship was observed (non-linear p = 0.347), indicating that higher intact PTH levels are associated with an elevated risk of sarcopenia." (PMID 39478830, 2024). "Notably, our study revealed a linear increase in sarcopenia risk with higher serum PTH levels, consistent with findings from the DOPPS analysis where groups with higher PTH levels experienced more significant weight loss over a year." (PMID 39478830, 2024). "PTH and its fragments can enhance muscle proteolysis, but it has not been determined if PTH elevations alone can cause sarcopenia." (PMID 38791164, 2024). "Clinical study findings indicate that high PTH levels increase the risk of sarcopenia in elderly women, and individuals with hyperparathyroidism have a higher prevalence of sarcopenia compared with those without." (PMID 37509715, 2023). "The present study provides clinical evidence regarding the effect of high PTH levels on muscle tissue, which may direct future research into the treatment of sarcopenia in CKD patients." (PMID 35573870, 2022). "Moreover, most of the subjects had appropriate medications to achieve optimal 25OH-D and PTH levels, hence eliminating differential levels as a factor and probably contributing to the lower incidence of sarcopenia in our study population." (PMID 34579163, 2021). "However, parathyroid hormone (PTH) was significantly higher in the non‐sarcopenia group than in the sarcopenia group (p = 0.015)." (PMID 34350631, 2021). "In the multivariate logistic regression, female gender, a lower BMI, and a lower Vit-D concentration were significantly correlated with sarcopenia, but only a higher PTH concentration significantly predicted that a participant was Sarc+ LVH+ (odds ratio: 1.05, 95% CI: 1.03–1.08, p < 0.005)." (PMID 28112206, 2017). "Through pathway enrichment analysis, we demonstrated that “purine metabolism”, “parathyroid hormone synthesis, secretion and action”, “choline metabolism in cancer”, and “tuberculosis” emerged as the most significantly perturbed pathways in new-onset sarcopenia." (PMID 38962681, 2024).
sarcopenia (continued). "However, the relationship between PTH dysregulation and sarcopenia in the PD population remains unclear." (PMID 39478830, 2024). "In conclusion, our study highlights elevated serum PTH levels, overhydration, and ASCVD as independent factors contributing to sarcopenia among prevalent PD patients." (PMID 39478830, 2024). "However, whether PTH interplays in the established pathogenesis of sarcopenia and myocyte changes, such as oxidative stress, inflammation, mitochondrial and satellite cell dysfunction, and myostatin overexpression, remains unexplored and should be addressed in further research." (PMID 39478830, 2024). "Moreover, PTH may be a potential therapeutic target for treating sarcopenia in CKD patients." (PMID 35573870, 2022). "Among the bone mineral metabolic parameters, serum calcium showed a significant negative correlation, and serum intact PTH showed a significant positive correlation with sarcopenia." (PMID 37685565, 2023). "Herein, we aimed to study FetA, Vit-D, and PTH concentrations in the elderly (≥65 years old) with or without sarcopenia and left ventricular hypertrophy (LVH)." (PMID 28112206, 2017). "In addition, vitamin D was lower in the sarcopenia group, and ALP and intact parathyroid hormone were higher." (PMID 26083479, 2015). "No study has investigated the role of parathyroid hormone synthesis in sarcopenia until now." (PMID 38962681, 2024). "Chronic renal illness is associated with several disturbances in metabolism and hormonal control—including MA, uraemia, and increased levels of parathyroid hormone (PTH) and insulin-like growth factor (IGF)—which affect muscle functionality and may influence the development of sarcopenia." (PMID 39126043, 2024). "PTH did not play any role in sarcopenia development or changes in muscle parameters." (PMID 37892452, 2023). "Third, since this is an exploratory study and not conducted to specifically investigate the association between phosphorus regulation and sarcopenia, we did not study factors influencing phosphorus regulation, such as FGF23, klotho, vitamin D, parathyroid hormone, and dietary intakes." (PMID 32438707, 2020).
depression (39 papers, 2010 to 2026). "Six studies investigated potential associations between the presence of depression and the levels of calcium, parathyroid hormone, or other endocrine parameters such as serum cortisol and bone formation marker osteocalcin in PHPT." (PMID 39997061, 2025). "In this article, we reported the association of a demographic feature, namely, gender, and laboratory result PTH level with increased risk of depression and anxiety." (PMID 38681457, 2024). "Logistic regression analysis of the significant risk of elevated PTH revealed that in the case of depression, for individuals with PTH levels >400 pg/ml, 34, 12, and 16 cases were classified as abnormal, borderline, and normal, respectively." (PMID 38681457, 2024). "Due to the negative impact of these mental disorders on daily life and overall well-being, further research is required to elucidate the underlying mechanisms of the relationship between elevated PTH levels and depression and anxiety in hemodialysis patients." (PMID 38681457, 2024). "Our findings align with existing research that indicates the association between depression and anxiety and iPTH levels, highlighting a potential correlation between these psychological factors and PTH levels in dialysis patients." (PMID 38681457, 2024). "Elevated PTH levels in dialysis patients have been consistently linked to heightened levels of depression and anxiety, significantly impacting the patient’s quality of life." (PMID 38681457, 2024). "Regarding the blood tests, the risk of depression was increased by 0.4% (OR = 1.004, 95%CI = 1.001–1.007) for every unit increase in PTH, but it decreased by 4% for each unit increase in Hb (OR = 0.960, 95% CI = 0.926–0.996) in the MHD patients." (PMID 37046867, 2023). "Multivariate logistic regression analysis also found that PTH was positively associated with the incidence of anxiety and depression in the MHD patients." (PMID 37046867, 2023). "It is proposed that a low level of vitamin D can lead to the elevation of PTH, which is associated with depression." (PMID 35982462, 2022). "High levels of PTH have been associated with impaired performance in cognitive tests and with depression." (PMID 24884774, 2014). "Contrary to previous studies showing an association between higher PTH concentrations and depression in adults, serum concentrations of PTH were not strongly associated with depressive symptoms in children in our study." (PMID 22211693, 2012). "Elevated PTH levels were associated with increased anxiety and depression in hemodialysis patients." (PMID 38681457, 2024). "Similarly, the findings on the potential link between high PTH levels and an increased prevalence of abnormal depression scores in hemodialysis patients align with existing research associating excess PTH with neuropsychiatric disturbances." (PMID 38681457, 2024). "RASi use was associated with fewer problems in the mobility and usual activities dimensions, whilst higher PTH (15.8–56.0 pmol/L) was associated with fewer issues in usual activities and anxiety and depression dimensions [compared with PTH low to normal (0–7.1 pmol/L)]." (PMID 38313684, 2024). "Therefore, the serum PTH >800 pg/ml was significantly associated with depression." (PMID 38681457, 2024). "Besides, depression is associated with lower vitamin D and increased parathyroid hormone levels, which may impact bone remodeling." (PMID 32050694, 2020). "Overall, the mechanisms connecting PHPT to the development of depression/anxiety are complex and involve both the direct and indirect effects of PTH and calcium." (PMID 39997061, 2025). "Overall, patients in the study group with serum PTH levels >400 pg/ml were more prone to the development of depression than the control group." (PMID 38681457, 2024). "The reason is that they raised an essential concern that pain and lack of sleep, which are the most common symptoms of elevated PTH, can lead to depression." (PMID 38681457, 2024).